NID1 (nidogen 1)
Description:
Sulfated glycoprotein widely distributed in basement membranes and tightly associated with laminin. Also binds to collagen IV and perlecan. It probably has a role in cell-extracellular matrix interactions.
Synonyms: NID; entactin
Tractability: Antibody: its Gene Ontology location is reachable by antibodies, with high confidence; UniProt places it where antibodies can reach, with medium confidence; UniProt predicts a signal peptide or a membrane-spanning region. PROTAC: its protein half-life has been measured.
Gene: Protein-coding gene on chromosome 1 (235,975,830 to 236,065,202, reverse strand). Ensembl gene ENSG00000116962.
Subcellular location: Secreted, extracellular space, extracellular matrix, basement membrane
Subcellular location (Human Protein Atlas): Vesicles; Mitotic spindle; Predicted to be secreted
Pathways (Reactome):
Extracellular matrix organization: Degradation of the extracellular matrix; Laminin interactions
Gene Ontology:
Molecular function: collagen binding; laminin binding; proteoglycan binding; extracellular matrix structural constituent; calcium ion binding; extracellular matrix binding; laminin-1 binding
Biological process: basement membrane organization; positive regulation of cell adhesion; positive regulation of integrin-mediated signaling pathway; positive regulation of muscle cell differentiation; regulation of basement membrane organization; cell-matrix adhesion
Cellular component: basement membrane; extracellular exosome; extracellular matrix; extracellular region; protein complex involved in cell-matrix adhesion; cell periphery
Genetic constraint (gnomAD): Loss-of-function variants: 72 observed, 129.56 expected, observed/expected ratio (o/e) 0.56, 90% interval 0.46 to 0.68. The upper end of that interval is the gene's LOEUF score, 0.68, which puts it in group 2 of 6, group 1 being the genes least tolerant of losing a copy. Missense variants: 1,505 observed, 1,711.1 expected, observed/expected ratio (o/e) 0.88, 90% interval 0.84 to 0.92. Synonymous variants: 662 observed, 688.8 expected, observed/expected ratio (o/e) 0.96, 90% interval 0.9 to 1.02.
Homologues: Orthologues: chimpanzee NID1 (99% identical), macaque NID1 (98% identical), dog NID1 (88% identical), pig NID1 (87% identical), mouse Nid1 (85% identical), rat Nid1 (85% identical), guinea pig NID1 (84% identical), tropical clawed frog nid1 (62% identical), zebrafish nid1b (49% identical), zebrafish nid1a (49% identical). Paralogues in human: NID2 (43% identical), LRP1 (22% identical), LRP1B (20% identical), LRP2 (19% identical), VLDLR (15% identical), LRP4 (14% identical), LRP8 (14% identical), EGF (13% identical), LRP6 (11% identical), LRP5 (11% identical), LRP3 (9% identical), and 2 more.
Diseases named in the same sentence as NID1 in open-access papers:
NID1 is named in the same sentence as 74 diseases in open-access papers, as found by Europe PMC text mining. Sharing a sentence is not in itself a finding about the gene and the disease. The quoted sentences say what the papers report.
breast cancer (16 papers, 2012 to 2025). A primary or metastatic malignant neoplasm involving the breast. "To date, the effect of mutations in nidogen genes in the human kidney is not known; however, quantitative mass spectrometry proteomics have identified that the NID1 gene, which encodes for nidogen-1, promotes lung metastases of breast cancer and melanoma." (PMID 29435440, 2018). "To further investigate these findings at the protein level, we performed western blot analysis of nidogen-1 protein expression in 4T1 breast cancer cells and CAFs." (PMID 41181108, 2025). "The data is consistent with our previous mass spectrometry findings that nidogen-1 is slightly downregulated in the primary breast cancer while substantially reduced in the metastatic lungs." (PMID 41181108, 2025). "We therefore initially focused on breast cancer and examined the nidogen-1 expression pattern in the 4T1 mouse model of breast cancer." (PMID 41181108, 2025). "It was also reported that NID1 enhances cell proliferation, migration, invasion, and promotes lung metastasis of breast cancer and melanoma." (PMID 35681609, 2022). "Recently, a study showed that suppression of NID1 expression reduces proliferation and migration/invasion in claudin-low murine mammary tumor cells." (PMID 34604366, 2021). "NID1 is a basement membrane with prometastasic characteristics, which it is also up-regulated in the lung metastasis of breast cancer cells." (PMID 34503180, 2021). "Previously, NID1 has been proposed as a new biomarker for disease progression and therapeutic target in breast cancer and melanoma." (PMID 33050649, 2020). "According to the information of the Human Protein Atlas, the protein level of NID1 in liver, colon, and lung and breast cancers are undatable or weakly positive." (PMID 33173740, 2020). "On one hand, a recent publication describes nidogen-1 as a promoter of metastasis to the lung in a breast cancer and melanoma model and high expression of nidogen-1 to correlate with an unfavourable prognosis in estrogen receptor negative breast cancer." (PMID 30947697, 2019). "With the demonstration of the anti-migratory effect of endothelial cell-derived nidogen-1 on SK-BR-3 breast cancer cells we add nidogen-1 to the regulators of endothelial control over cancer cell migration." (PMID 30947697, 2019). "We previously identified nidogen-1 as strongly downregulated in metastases of the lungs compared to healthy lung tissue, using mass spectrometry analysis of decellularized organs obtained from the 4T1 syngeneic mouse model of breast cancer." (PMID 41181108, 2025). "Using orthotopic and transgenic mouse models of breast cancer, we demonstrated that nidogen-1 expression is reduced in mammary tumors and in distant lung metastases, and that the development of CAFs may be accountable for these changes." (PMID 41181108, 2025). "Nidogen 1 is a protein that interacts with several components of the extracellular matrix and its overexpression is known to correlate with drug resistance in ovarian cancer and increased metastasis in women affected with Breast Cancer." (PMID 34796107, 2021). "NID1 gene was found to be a new therapeutic target biomarker in breast cancer and EC invasion." (PMID 32315343, 2020). "In contrast to decreased TGFBI that has previously been associated with DCIS, decreased CADM3, DPT, and NID1 have not previously been linked to breast cancer." (PMID 23236365, 2012). "In this study, we have identified high frequencies of cancer specific abnormal hypermethylation of the parts of promoter regions of integrin ITGA1, ITGA4, ITGA9, and nidogen NID1, NID2 genes in breast cancer." (PMID 33500458, 2021). "To investigate this further, we obtained nidogen-1 knockout mice and switched to a melanoma model given this previous report and the strain of the mice (not syngeneic with the breast cancer models)." (PMID 41181108, 2025).
breast cancer (continued). "We injected 4T1 breast cancer cells expressing histone H2B-GFP into the mammary fat pad of syngeneic BALB/c mice and stained the border region of the 4T1 tumors and healthy fat pad with both nidogen-1 and collagen IV antibodies to visualize the BM." (PMID 41181108, 2025). "The authors observed that Nidogen-1 (NID-1), a basement membrane glycoprotein with binding sites for other ECM molecules, promote lung metastasis of breast cancer and melanoma and induces prometastatic characteristics, and its expression is correlated with poor prognosis." (PMID 31528221, 2019). "We found that one cell line of epithelial origin (the breast cancer cell line 4T1) and two cell lines of neural crest origin (the melanoma cell lines HCmel12 and B16F10) do not express nidogen-1." (PMID 41181108, 2025). "Similarly, it was shown that tumors formed by the human breast cancer MDA-MB-231 cell line, and by its counterpart MDA-MB-231-LM2 cell line which prefers to colonize lungs, the nidogen-1 expression is restricted to the stromal cells and not the cancer cells." (PMID 41181108, 2025).
ovarian carcinoma (15 papers, 2017 to 2025). A malignant neoplasm originating from the surface ovarian epithelium. "In the previous ovarian cancer relevant proteomic study, we found NID1 was a candidate diagnostic biomarker for ovarian cancer; it is elevated in the peripheral blood of ovarian cancer patients compared to normal controls." (PMID 28416770, 2017). "In the present study, we demonstrated that NID1 was a mesenchymal associated gene and its high expression was significantly correlated with shorter overall survival of ovarian cancer patients." (PMID 28416770, 2017). "In summary, our study shows that NID1 is a mesenchymal associated gene and is significantly correlated with poor prognosis of ovarian cancer." (PMID 28416770, 2017). "Together, these data suggest a positive role of NID1 in the motility and invasiveness of ovarian cancer cells associated with partial EMT process." (PMID 28416770, 2017). "Nidogen-1 (NID1) has been identified as a novel candidate diagnostic biomarker of ovarian cancer in our previous study." (PMID 28416770, 2017). "This will involve the disassembly of several extracellular matrix complexes: in ovarian cancer cells NID1 plays a key role in this EMT transition." (PMID 38875182, 2024). "A previous study has indicated that NID1 promotes the epithelial-mesenchymal transition (EMT) in ovarian cancer." (PMID 32355035, 2020). "We previously demonstrated that NID1 was elevated in the peripheral blood of ovarian cancer patients compared to normal controls." (PMID 28416770, 2017). "Our recent data revealed that NID1 induces ERK phosphorylation in ovarian cancer cells (unpublished to date)." (PMID 28555007, 2017). "Herein we proposed that NID1 exacerbated resistance of ovarian cancer cells via upregulating the expression of MDR1 and ABCG2, two well-known ABC transporters." (PMID 28416770, 2017). "The relevance of its high expression and the Spindle as well as the “mesnencymal” subtype shows that NID1 probably imparts EMT-prone phenotype to ovarian cancer cells." (PMID 28416770, 2017). "Taking the relevance of EMT with chemoresistance of cancer cells into consideration, we further investigated the effects of NID1 on cisplatin-based resistance in ovarian cancer cells." (PMID 28416770, 2017). "In this study, we present the first evidence that NID1 promotes the migration, invasion and chemoresistance of ovarian cancer cells via EMT and its molecular mechanism involves the activation of ERK/MAPK signaling." (PMID 28416770, 2017). "The effect of NID1 is limited, therefore these ovarian cancer cells separately retain partial intrinsic characteristics during the transition to their opposite phenotype." (PMID 28416770, 2017). "Collectively, our findings have uncovered the molecular mechanisms of NID1 in promoting ovarian cancer metastasis and chemoresistance, and provide a rationale for the therapeutic potential of NID1 suppression in ovarian cancer." (PMID 28416770, 2017). "As an example, the expression level of CD44 (one ovarian cancer stem cell marker) was increased in NID1-overexpressed OVCAR-3 cells but decreased in NID1-depleted HEY cells." (PMID 28416770, 2017). "EMT is currently considered as a key event for tumor metastasis, we next determined the effect of NID1 on ovarian cancer cell migration and invasion." (PMID 28416770, 2017). "Moreover, NID1 plays a critical role in ovarian cancer cell migration, invasion and chemoresistance by partial EMT process." (PMID 28416770, 2017). "Nevertheless, the role of NID1 in the pathogenesis of ovarian cancer is unclear." (PMID 28416770, 2017). "Moreover, high expression of NID1 was correlated with shorter overall survival of ovarian cancer patients (P<0.05)." (PMID 28416770, 2017). "Taking a close relationship between cancer metastasis, EMT and basement membrane into consideration, we wondered whether NID1 involved in ovarian cancer EMT and thus metastasis." (PMID 28416770, 2017).
ovarian carcinoma (continued). "We demonstrated NID1 promoted ovarian cancer cell migration and invasion." (PMID 28416770, 2017). "It indicates that NID1 silencing induces a partial MET process in ovarian cancer cells." (PMID 28416770, 2017). "The present results lend support to the EMT-promoting role of NID1 in ovarian cancer." (PMID 28416770, 2017). "Furthermore, NID1 promoted the EMT process of ovarian cancer cells whereby they lose their epithelial characteristics and acquire certain mesenchymal properties." (PMID 28416770, 2017). "Also in ovarian cancer, nidogen-1 has been shown to promote EMT and metastasis." (PMID 30947697, 2019). "In addition, we found NID1 favored cisplatin-based resistance of ovarian cancer, with refractory patients having the higher expression level of NID1, NID1-overexpressed cells having higher cisplatin resistance and NID1-silencing cells having weaker cisplatin resistance." (PMID 28416770, 2017). "Thus, we hypothesized that the EMT-promoting function of NID1 in ovarian cancer cells might result from the activation of ERK/MAPK pathway." (PMID 28416770, 2017). "Thus, NID1 may represent a candidate prognostic indicator and a potential therapeutic target of ovarian cancer." (PMID 28416770, 2017). "NID1, another EMT marker, is essential for metastasis and chemoresistance in ovarian cancer and claudin-low cancers." (PMID 40297587, 2025). "Nidogen 1 (NID1) is an extracellular matrix protein that promotes epithelial-mesenchymal transition (EMT) and metastasis in ovarian cancer." (PMID 35757695, 2022). "To obtain further insights into the EMT-promoting capability of NID1 in ovarian cancer, we first generated the stable OVCAR-3 monoclone with ectopic expression of NID1." (PMID 28416770, 2017). "Besides NID1, several regulators, such as HPIP, NANOG and FOXM1, have been reported to promote EMT of ovarian cancer cells and then confer them drug resistance, involving PI3K/AKT pathway, STAT3 pathway, etc." (PMID 28416770, 2017).
melanoma (11 papers, 2012 to 2025). A malignant, usually aggressive tumor composed of atypical, neoplastic melanocytes. "Using the HCmel12 melanoma model, we found that loss of stromal nidogen-1 causes increased lung metastasis." (PMID 41181108, 2025). "The lung metastasis of NID1– or 2–deficient mice were studied after being intravenously injected with B16 murine melanoma cells." (PMID 34976811, 2021). "On the other hand, the NID1 locus has been described in a genome-wide association study to be linked with the risk of developing melanoma with a decreased expression of nidogen-1 in nevi and melanoma patients." (PMID 30947697, 2019). "We investigated the role of stromal-derived nidogen-1 in melanoma lung metastasis using wildtype and nodogen-1 knockout mice." (PMID 41181108, 2025). "Although NID1 has been found in EVs of melanoma cells, nasopharyngeal carcinoma cells, and urine of healthy individuals, yet their roles in human cancers and normal physiology have not been reported." (PMID 33173740, 2020). "Using HCmel12 melanoma experimental metastasis model, we found that the nidogen-1 knockout mouse has increased lung metastasis, suggesting that nidogen-1 expression at the metastatic niche may be important to prevent cancer cell colonization of the lungs." (PMID 41181108, 2025). "This surprising difference may be attributed to the divergent interactions of these two melanoma cell lines with their respective microenvironments, or the difference in genetic backgrounds of the nidogen-1 knockout mice used in these two studies." (PMID 41181108, 2025). "NID1 is a basement membrane glycoprotein that is involved in ECM cellular interactions, cell migration and invasion, promotes melanoma metastasis, and is correlated with poor clinical outcomes." (PMID 33050649, 2020). "It has been reported that nidogen-1 knockout mice do not have increased lung metastasis compared to nidogen-1 wildtype or heterozygous mice in a B16 melanoma tail vein injection model." (PMID 41181108, 2025). "The authors demonstrated that the depletion of NID2, but not NID1, facilitates melanoma cell lung metastasis." (PMID 34976811, 2021).
gastric cancer (7 papers, 2007 to 2025). A primary or metastatic malignant neoplasm involving the stomach. "Loss of nidogen-1 by aberrant promoter methylation has also been linked to development of colon and stomach cancer, and also in prostate cancer loss of nidogen-1 increased tumour growth and metastasis." (PMID 30947697, 2019). "The analysis of various gastric cancer cell lines and gastric cancer patient samples also revealed a positive association between ELK3 and BMP1, LOXL2, SNAI1, SERPINF1, DCN, and NID1, and these genes were associated with a poor prognosis." (PMID 35409069, 2022). "First, the correlation between ELK3 expression and BMP1, LOXL2, SNAI1, SERPINF1, DCN, and NID1 expression was analyzed in 19 different gastric cancer cell lines." (PMID 35409069, 2022). "The gene analysis of samples from patients with gastric cancer indicated that a high ELK3 expression is positively correlated with BMP1, LOXL2, SNAI1, SERPINF1, DCN, and NID1 expression, all of which are closely associated with a poor prognosis." (PMID 35409069, 2022). "In primary tumors, we detected NID1 promoter methylation in 67% of colon cancer samples and in 90% of gastric cancers." (PMID 17328794, 2007). "For the NID1 gene, we detected promoter methylation in 67% (33/49) of the colon and 90% (18/20) of the gastric carcinoma samples." (PMID 17328794, 2007). "Patients with gastric cancer with a high expression of BMP1, LOXL2, SNAI1, SERPINF1, DCN, and NID1 had a poor prognosis." (PMID 35409069, 2022). "In gastric cancer, JQ1 downregulates chromatin accessibility and inhibits the RUNX2/NID1 signaling pathway, thereby preventing gastric cancer progression." (PMID 35965507, 2022). "The ELK3 expression in gastric cancer cells and human gastric cancer samples positively correlated with that of BMP1, LOXL2, SNAI1, SERPINF1, DCN, and NID1, suggesting that this gene signature may be predictive molecular markers for aggressive gastric cancer progression." (PMID 35409069, 2022). "Notably, the analysis of patients with gastric cancer indicated the marked positive regulation of ELK3 and BMP1, LOXL2, SNAI1, SERPINF1, DCN, and NID1 gene expression, suggesting a significant positive correlation between ELK3 and ECM remodeling-associated genes in gastric cancer." (PMID 35409069, 2022).